TLR4 (toll like receptor 4)
Diseases named in the same sentence as TLR4 in open-access papers (continued):
Sharing a sentence is not in itself a finding about the gene and the disease.
neuroblastoma (17 papers, 2006 to 2024). Neuroblastoma (NB) is the most common solid, extracranial childhood tumor. "Upon stimulation of human neuroblastoma M17 cell cultures with the TLR4 agonist LPS we found that IRF7 knockdown was sufficient to ablate the type-1 IFN response to the bacterial endotoxin." (PMID 25879763, 2015). "Here, we discuss a possible mechanism of the unresponsiveness of intracellular TLR-4-expressing NB-1 neuroblastoma cells to LPS." (PMID 17156435, 2006). "In the present study we have demonstrated that NB-1 and SK-N-SH neuroblastoma cells express intracellular TLR-4." (PMID 17156435, 2006). "To exclude the exceptional expression of TLR4 in NB-1 cells, we examined TLR4 expression in another human neuroblastoma cell line SK-N-SH." (PMID 17156435, 2006). "Further studies must be necessary to confirm the expression and role of TLR4 in neuroblastoma cells and neuroblasts." (PMID 17156435, 2006). "In this study, we investigated the expression of TLR4 in human neuroblastoma NB-1 cell line." (PMID 17156435, 2006). "There is little information on the expression and function of TLR4 in neuroblastoma cells." (PMID 17156435, 2006). "RT-PCR analysis demonstrated that SK-N-SH cell line as well as NB-1 cell line expressed TLR4 mRNA, suggesting that two neuroblastoma cell lines might commonly express TLR4." (PMID 17156435, 2006). "Therefore, there seemed to be a difference in TLR4 expression among various neuroblastoma cell lines." (PMID 17156435, 2006). "NB-1 neuroblastoma cells express TLR4, MD2, CD14 and MyD88, which are required for LPS signaling." (PMID 17156435, 2006). "Although TLR2 and TLR4 is usually expressed on the cell surface of immune cells, there are a number of reports on intracellular expression of these receptors in various cell types such as coronary artery endothelial cells, intestinal epithelial cells and neuroblastoma cell line." (PMID 24966802, 2014). "Although TLR4 has been reported to be expressed on the surface of most cell types, it is also localized in the intracellular compartments of several types of cells including intestinal epithelial cells, placental syncytiotrophoblasts, dendritic cells, and neuroblastoma cells." (PMID 23028952, 2012). "Here, we investigated the impact of palmitic acid on insulin responsiveness and its potential effects on TLR4 expression and resistin action in human SH-SY5Y neuroblastoma cell line." (PMID 33686181, 2021). "It was also recently observed that the anthocyaninidin, cyanidin, modulates inflammatory responses through decreasing expression of toll-like receptor 4 (TLR4), which lies upstream of NF-κB activation, in neuroblastoma cells treated with amyloid beta protein." (PMID 31443476, 2019). "Other similar works found that extracellular HMGB1 can act extrinsically on its membrane receptor TLR-4 to facilitate the signaling of pro-survival factors in neuroblastoma, and HMGB1/TLR-4 signaling would be activated to inhibit cell apoptosis in cortex of rats with brain injury." (PMID 32708917, 2020). "Notably, in models of apoptosis in human neuroblastoma cells and ischemia-reperfusion injury in retina, argon was proven to mediate neuroprotection via inhibiting TLR2 and TLR4." (PMID 31159847, 2019). "Nevertheless, a recent study unveiled that neuroblastoma NB-1 cells expressed intracellular TLR-4 but not the cell surface form." (PMID 24205354, 2013). "In the present study, we examined two neuroblastoma cell lines to confirm the lack of TLR-4 expression in neuroblatoma cells." (PMID 17156435, 2006). "Surprisingly, we found that NB-1 neuroblastoma cells expressed intracellular TLR-4 but did not respond to LPS." (PMID 17156435, 2006). "In this report we for the first time demonstrate that neuroblastoma cells express TLR4 at the cytoplasm but not at the cell surface." (PMID 17156435, 2006).
neuroblastoma (continued). "In a separate in vitro experiment, we found a marked elevation and secretion of LCN2 protein after application of LPS (a TLR4 activator) on a murine neuroblastoma cell line N2A (data not shown), suggesting the existence of the LCN2 regulation pathway in neurons." (PMID 35413913, 2022). "Human NB-1 neuroblastoma cells expressed intracellular form of TLR4, but not the cell surface form." (PMID 17156435, 2006). "On the other hand, SHSY-5Y neuroblastoma cells are reported to express no TLR4 at mRNA level." (PMID 17156435, 2006). "By using RT-PCR, we investigated whether human neuroblastoma cell line NB-1 expresses TLR4 or not." (PMID 17156435, 2006). "Considering that neuroblastoma cells do not express TLR-4, neuroblasts are unlikely to express TLR-4." (PMID 17156435, 2006).
pancreatitis (17 papers, 2009 to 2026). Inflammation of the pancreas. "The initial insult of pancreatitis results in the production of key ligands for TLR4 such as HMGB1 and heat shock proteins associated with sterile inflammation." (PMID 38585277, 2024). "This plays a significant role in the progression of pancreatitis as TLR4 deficient mice demonstrated much slower progression of pancreatic inflammation when compared to WT mice." (PMID 38585277, 2024). "The inhibition or loss of MIF resulted in lower TLR4 expression in the lungs of mice following the induction of pancreatitis as well as increased survival outcomes further implicating TLR4 in respiratory distress following the onset of pancreatitis." (PMID 38585277, 2024). "In fact, mice deficient in TLR4 or NOD1 are highly resistant to induction of experimental pancreatitis." (PMID 35967861, 2022). "Surprisingly, TLR4 expression was significantly higher in the pancreatitis-associated DHAV-1 and classical-type DHAV-1 groups than in the mock-infected group, with an increase of 51.63- and 38.59-fold, respectively." (PMID 34482448, 2021). "Previous studies reported that quercetin intervention exerted therapeutic effects on pancreatitis, intestinal injury and inflammation by inhibiting the activation of TLR4/MyD88/P38 MAPK pathway by up-regulating miR-216b and endoplasmic reticulum stress." (PMID 39946409, 2025). "Carbon monoxide releasing molecule has been found to inhibit TLR4 signaling in macrophages leading to reduced production of TNFα and proinflammatory cytokines in cerulein-induced pancreatitis." (PMID 38585277, 2024). "TLR4 has a role in the production of NETs, which are shown to be increased in the progression of pancreatitis and play a role in destruction of exocrine tissue." (PMID 38585277, 2024). "TLR4-/- mice also showed significantly less lung myeloperoxidase activity following the cerulein induction of pancreatitis." (PMID 38585277, 2024). "Knockout of TLR4 prevented the progression of acute edematous pancreatitis to acute necrotizing pancreatitis with the administration of cerulein and LPS." (PMID 38585277, 2024). "Clarification of the role of SOCS3 and TLR4 in macrophage polarization is also of interest in the progression of pancreatitis as deletion of SOCS3 resulted in more beneficial outcomes following induction of pancreatitis." (PMID 38585277, 2024). "(2012), who found that the gut microbiota mediated cerulein-induced pancreatitis through activation of pancreatic acinar NOD1 to a much greater extent than TLR4." (PMID 35811665, 2022). "Compared with wild-type mice, TLR4-/- mice reportedly show less pancreatic damage and inflammation in pancreatitis, which supports the importance of TLR4 in the pathogenesis of pancreatitis." (PMID 34589510, 2021). "Toll-like receptor 4 (TLR4) is widely expressed in the pancreatic tissues and plays an important role in pancreatitis." (PMID 31998444, 2020). "In this study, we demonstrated that the mRNA and protein expression of TLR4 markedly increased in caerulein-induced pancreatitis." (PMID 28592850, 2017). "In the context of the pancreas, TLR4−/− mice were found to have reduced apoptosis in a surgical model of pancreatitis." (PMID 19357791, 2009). "This also shows that reduction in production of IL-8 through the inhibition of TLR4 signaling could result in improved pancreatitis outcomes." (PMID 38585277, 2024). "As markers such as IL-6 has proven to be significantly altered when looking at the severity of pancreatitis, TLR4 signaling could have a role in the progression of this disease." (PMID 38585277, 2024). "An E. coli MG1655 mono-colonized pancreatitis rat model demonstrated more severe pancreatic injury as compared to a normal pancreatitis rat model with significant upregulation of the TLR-4-mitogen-activated protein pathway and activation of the ERS pathway in intestinal epithelial cells." (PMID 36232419, 2022).
pancreatitis (continued). "Another outcome of TLR4 signaling is the production of macrophage migration inhibitory factor (MIF), which has been shown to be a significant indicator of the severity of pancreatitis in both humans and mice." (PMID 38585277, 2024). "Therefore, targeting of TLR4 upstream of caspase-1 could at least partially inhibit cleaving and activation of caspase-1, which would result in more beneficial outcomes to those suffering from pancreatitis." (PMID 38585277, 2024). "An important downstream target of TLR4 signaling in pancreatitis is TRAF6, which is involved in both the TLR4 dependent and TLR4 independent pathways." (PMID 38585277, 2024). "Among TLRs, TLR4 and TLR9 play critical roles in pancreatitis through inflammasome activation." (PMID 28592850, 2017). "Recognition of gut Gram-negative bacteria by toll-like receptor 4 (TLR4) and nucleotide-binding oligomerization domain 1 (NOD1) expressed by pancreatic acinar cells and immune cells causes pro-inflammatory cytokine responses in experimental pancreatitis." (PMID 35967861, 2022).
pneumococcal infection (17 papers, 2008 to 2023). Infections with bacteria of the species streptococcus pneumoniae. "Histopathological examination of the lungs showed more severe lung injury in the gut microbiota-disrupted wild-type mice compared to the undisrupted controls after pneumococcal infection, which was considerably less in the corresponding TLR4-deficient mice." (PMID 30562386, 2018). "The effect of gut microbiota disruption on pulmonary bacterial clearance in wild-type and TLR4-deficient mice after pneumococcal infection." (PMID 30562386, 2018). "Both survival and pulmonary clearance of S. pneumoniae were lower in the TLR4-deficient mice with disrupted gut microbiota, compared to their intestinally healthy counterparts after pneumococcal infection." (PMID 30562386, 2018). "The effect of gut microbiota disruption on survival in wild-type and TLR4-deficient mice after pneumococcal infection." (PMID 30562386, 2018). "Our previous research identified a pneumolysin variant (ΔA146Ply), a Toll-like receptor 4 agonist, that was an effective adjuvant in the protection of fusion protein DnaJ-ΔA146Ply against mucosal Streptococcus pneumoniae infections." (PMID 28659923, 2017). "TLR4+896 mutants cause hypo-responsiveness to LPS and enhance susceptibility to invasive meningococcal and pneumococcal infections." (PMID 22662111, 2012). "TLR4+896 mutants are also associated with an increased risk of developing invasive disease in patients with pneumococcal infections." (PMID 22662111, 2012). "The TLR4 pathway is involved in the reduced pulmonary resistance to S. pneumoniae caused by gut microbiota disruption, and therefore is a potential target for the management and control of pneumococcal infections." (PMID 30562386, 2018). "We found that the survival and pulmonary bacterial clearance were lower in the gut microbiota-disrupted TLR4-deficient mice compared to the undisrupted controls after pneumococcal infection, but the degree of decline was much lower compared to the wild-type mice." (PMID 30562386, 2018). "TLR4 rs4986790 mutated variant due to hyporesponsiveness to LPS may cause susceptibility to invasive meningococcal and pneumococcal infections." (PMID 29754263, 2018). "Interestingly, the role of TLR4 seems to be specific to the nasopharynx as TLR4-deficient mice exhibit only a modest impairment of host defense following direct pneumococcal infection of the lower respiratory tract." (PMID 21108806, 2010). "It remains somewhat controversial whether TLR4-deficiency confers susceptibility or tolerance to pneumococcal infection in vivo." (PMID 18664270, 2008). "Our study provides an experimental basis for novel therapeutic strategies against pneumococcal infection that exploit the TLR4 pathway." (PMID 30562386, 2018). "BALB/c mice, which were used as a background strain of TLR4 KO mice in our current experiment, were known as resistant strain in pneumococcal infection compared to other strains." (PMID 18664270, 2008). "As macrophage depletion in secondary pneumococcal infection increases pneumococcal dissemination, increased TLR4 expression may be beneficial in reducing its capacity to spread." (PMID 32318074, 2020). "In the present study, the TLR4-deficient mice had lower TNF-α and IL-1β levels and decreased pulmonary resistance after S. pneumoniae infection compared to wild-type mice, indicating that the TLR4 pathway mediates the immune response against pneumococcal infection." (PMID 30562386, 2018). "The interaction between pneumolysin and TLR4 has been found to limit the growth of pneumococci in the nasopharynx in a model of colonization whereas TLR4 may also contribute to antibacterial defense during pneumococcal infection of the lower airways." (PMID 25700108, 2015). "The protective role of TLR2, TLR4, and TLR9 against pneumococcal infection is suggested by the results obtained from studies using either TLR2, TLR4, or TLR9 knockout or mutant mice." (PMID 35281442, 2022).
pneumococcal infection (continued). "The innate immune response of TLR2/TLR4 double-knockout mice to intracisternal pneumococcal infection was more severely impaired than that of mice lacking only TLR2 or TLR4." (PMID 22662111, 2012). "Although there is strong evidence to support that TLR4 is a critical receptor for recognizing pneumolysin and pneumolysin is a major virulence factor of pneumococcal infection, the role of TLR4 in pneumococcal infection is not fully understood." (PMID 18664270, 2008). "Moreover, FSTL1 was expressed after Streptococcus pneumoniae infection, positively modulated the NLRP3 (NACHT, LRR, and PYD domain-containing protein 3) inflammasome, and promoted inflammatory injury during infection through the TLR4/NF-κB signaling pathway." (PMID 37322475, 2023).
candidiasis (16 papers, 2007 to 2025). Infection with the organism Candida. "Variants in TLR2 and TLR4 have been associated with altered immune responses to Candida infections, suggesting that genetic predisposition plays a role in the pathogenesis of RVVC." (PMID 41295183, 2025). "The low PCs in candidiasis and increased expression of TLR4 is associated with crosstalk between polymorphonuclear cells (mainly neutrophils) and ECs." (PMID 36899343, 2023). "While TLR2 has been shown to be essential for defense against C. albicans, contrasting results were reported with TLR2 KO mice being resistant to candidiasis whereas TLR4 KO mice were susceptible." (PMID 18606009, 2008). "TLR4 also enhances adaptive immunity to candidiasis by promoting the differentiation and function of Th17 cells." (PMID 38003833, 2023). "TLR4 is important for innate immunity to candidiasis, inducing the production of pro-inflammatory cytokines by macrophages and dendritic cells." (PMID 38003833, 2023). "In humans, polymorphisms in TLR1, TLR4, and TLR6 have been suggested to confer greater susceptibility to systemic candidiasis in acutely ill patients in the intensive care unit (ICU) in some studies." (PMID 34964702, 2022). "Of the TLRs, TLR2 and TLR4 play important roles in the pathogenesis of candidiasis, such that they induce proinflammatory responses in a synergistic manner with specific CLRs." (PMID 33919079, 2021). "Among the TLR family, mainly TLR2 and TLR4, are involved in the host interaction with C. albicans and play a significant role in the development of host immune responses during candidiasis." (PMID 24391778, 2013). "There is some evidence that a TLR-4 mediated interplay between PMNs and epithelial cells is important for the protective response against Candida infections but the exact mechanisms remained elusive." (PMID 19523197, 2009). "Furthermore, TLR2 and TLR4 have previously been reported to mediate host response to other fungi such as candidiasis, Aspergillus, and Cryptococcus neoformans." (PMID 17982419, 2007). "CLRs, such as Dectin-1 and DC-SIGN; TLRs, such as TLR2 and TLR4; and other receptors such as Galectin-3 and CR3 have all been shown to play a role in Candida infection." (PMID 33562068, 2021). "TLR4 showed a downward trend, although it did not present significance between the control group and the group with candidiasis." (PMID 38525710, 2024). "The protective effect of C. albicans EVs in a mouse model of systemic candidiasis was lost in mice lacking TLR4, indicating that EV vaccination is TLR4-dependent." (PMID 39555918, 2024). "A recent study demonstrated that a wild-type strain of Candida induced TLR2, TLR4, TLR6, and TLR9 gene expression activation in the epithelial cells showing that different receptors may play important roles in candidiasis." (PMID 32466609, 2020).